UNKL (unk like zinc finger)
Description:
May participate in a protein complex showing an E3 ligase activity regulated by RAC1. Ubiquitination is directed towards itself and possibly other substrates, such as SMARCD2/BAF60b. Intrinsic E3 ligase activity has not been proven.
Synonyms: C16orf28; ZC3H5L; ZC3HDC5L; FLJ23360
Tractability: PROTAC: UniProt records ubiquitination sites on it.
Gene: Protein-coding gene on chromosome 16 (1,363,205 to 1,414,751, reverse strand). Ensembl gene ENSG00000059145.
Subcellular location: Cytoplasm (Isoform 4); Nucleus
Subcellular location (Human Protein Atlas): Cytosol
Pathways (Reactome):
Immune System: Antigen processing: Ubiquitination & Proteasome degradation
Gene Ontology:
Molecular function: protein binding; metal ion binding
Biological process: protein ubiquitination
Cellular component: cytosol; cytoplasm; nucleus
Genetic constraint (gnomAD): Loss-of-function variants: 58 observed, 54.99 expected, observed/expected ratio (o/e) 1.05, 90% interval 0.85 to 1.31. The synonymous counts are far from expectation, so gnomAD's model fits this gene poorly and the ratio says little. Missense variants: 1,097 observed, 843.07 expected, observed/expected ratio (o/e) 1.3, 90% interval 1.24 to 1.37. Synonymous variants: 588 observed, 401.47 expected, observed/expected ratio (o/e) 1.46, 90% interval 1.37 to 1.57.
Homologues: Orthologues: chimpanzee UNKL (99% identical), guinea pig UNKL (88% identical), mouse Unkl (87% identical), pig UNKL (84% identical), dog UNKL (82% identical), macaque UNKL (80% identical), rat Unkl (77% identical), tropical clawed frog unkl (70% identical), zebrafish unkl (65% identical), Drosophila melanogaster unk (39% identical), Caenorhabditis elegans unk-1 (35% identical). Paralogues in human: UNK (55% identical).
Diseases named in the same sentence as UNKL in open-access papers:
UNKL is named in the same sentence as 6 diseases in open-access papers, as found by Europe PMC text mining. Sharing a sentence is not in itself a finding about the gene and the disease. The quoted sentences say what the papers report.
mucolipidosis (1 paper, 2022). A group of inherited lysosomal storage diseases characterized by accumulation of lipids and carbohydrates in the tissues, resulting in mental disabilities and skeletal malformations. "UNKL is associated with mucolipidosis, while the function and role of C16orf91 have not been reported." (PMID 35990977, 2022).
neuroblastoma (1 paper, 2015). Neuroblastoma (NB) is the most common solid, extracranial childhood tumor. "Among the neuroblastoma genes, RAD54B, BBS9 and UNKL were detected in exosomes while BBS9, IGFN1 and PKD1L3 were identified in ectosomes." (PMID 25944692, 2015).
cancer (2 papers, 2022 to 2024). A tumor composed of atypical neoplastic, often pleomorphic cells that invade other tissues. "By far, little is known about the relevance of C4orf17 (harboring cg26647453) and UNKL (harboring cg26728422) in cancers." (PMID 37830163, 2024). "As shown in the heatmaps, the hsa_circ_0001495, miR-125b-5p, and GPM6A were down-regulated in cancer tissues compared to their paired para-carcinomal tissues of HCC, whereas hsa_circ_0000688, miR-106b-5p, and four mRNAs (UNKL, GPRIN1, SMYD5, AURKB) were up-regulated." (PMID 35002514, 2022).
UNKL also shares sentences with these, for which no sentence is quoted: breast carcinoma (1 paper); dilated cardiomyopathy (1); osteosarcoma (1).